KIF1A (kinesin family member 1A)
Diseases named in the same sentence as KIF1A in open-access papers (continued):
Sharing a sentence is not in itself a finding about the gene and the disease.
Brain atrophy (2 papers, 2023). Partial or complete wasting (loss) of brain tissue that was once present. "A partially overlapping phenotype-brain atrophy with progressive encephalopathy was recently found to be associated with de-novo KIF1A mutations." (PMID 37259299, 2023).
cognitive decline (2 papers, 2019 to 2022). "In the present study, a dominant KIF1A variant localised in the motor domain of the protein was found in a female proband and her mother with childhood onset complex HSP and cognitive decline." (PMID 30778698, 2019).
generalized epilepsy (2 papers, 2020 to 2022). Epilepsy that is characterized by generalized seizure types and may have typical interictal and/or ictal EEG findings that accompany generalized seizure types (for example generalized spike-wave). "In our study, we identified a rare mutation of KIF1A in a family with six patients over three generations who presented with generalized epilepsy." (PMID 32174959, 2020).
intracerebral hemorrhage (2 papers, 2017 to 2019). A cerebrovascular disorder characterized by bleeding into one or both cerebral hemispheres including the basal ganglia and the cerebral cortex. "This study aimed to identify the roles of netrin-1 and KIF1A in secondary brain injury after intracerebral hemorrhage (ICH) and the potential mechanisms." (PMID 29375318, 2017). "However, UNC-104/KIF1A has been implicated in trafficking of its homologue UNC-6 in C. elegans and in rats with intracerebral hemorrhage, KIF1A abolishment led to attenuation of netrin-1-related functions." (PMID 31616253, 2019).
neuroblastoma (2 papers, 2019 to 2021). Neuroblastoma (NB) is the most common solid, extracranial childhood tumor. "In the absence of a cell line model carrying the variant R169T, we ectopically expressed the WT and mutant KIF1A forms in SH-SY5Y neuroblastoma cells and determined protein stability by western blot." (PMID 34121983, 2021). "A set of six markers (CCND1, DDC, GABRB3, ISL1, KIF1A, PHOX2B) was identified by genome-wide gene expression microarray analyses of 48 neuroblastoma tumors and nine remission BM samples followed by selecting genes with higher tumor-to-BM expression ratios." (PMID 31214500, 2019).
viral infection (2 papers, 2020 to 2025). "Of note, Kif1a-mNG expression varied from cell to cell, but was independent of viral infection." (PMID 31995633, 2020).
α-synucleinopathy (2 papers, 2013 to 2023). "In a rat model of α-synucleinopathy, elevated levels of KIF1A were observed in substantia nigra, suggesting the possibilily of the imbalance in protein degradation and synthesis and/or axonal transport deficit." (PMID 37063368, 2023). "In a rat model of α-synucleinopathy, elevated levels of KIF1A were observed in substantia nigra, and the authors suggested the possibility that accumulation of these motor proteins may be due to the imbalance in protein degradation and synthesis or to axonal transport deficit." (PMID 23776493, 2013).
-motor polyneuropathy (1 paper, 2025). "Among them, patients carrying KIF1A (p.G321D) show pure HSP, while patients carrying KIF1A (p.E19K, p.R316Q) show compound HSP with axonal sensory-motor polyneuropathy." (PMID 40964093, 2025).
aortic valve disease (1 paper, 2020). "Although the balanced translocation in this patient with left-sided heart defects may be a coincidental finding, the observation in this study that overexpression of Kif1A in Drosophila phenocopies at least one of the primary cardiac defects in the patient, i.e., aortic valve disease, is compelling." (PMID 32498427, 2020).
autonomic neuropathy (1 paper, 2014). An inherited or acquired peripheral neuropathy affecting the autonomic nervous system. "Specifically, motor domain lesions (A255V and R350G) in human KIF1A underlie the molecular basis of the rare recessive late onset spastic paraplegia SPG30 and a frameshift mutation in the PH domain underlies a form of hereditary sensory and autonomic neuropathy." (PMID 25329901, 2014).
colon cancer (1 paper, 2021). "The three most significant novel genes identified in MSI-H vs MSS/MSI-L tumors that were subsequently replicated in colon cancer cell lines were AGMO, LINC02577 and KIF1A, all of which displayed reduced expression in MSI-H cell lines and tumors compared to MSS/MSI-L cell lines and tumors." (PMID 33889300, 2021).
congenital heart disease (1 paper, 2020). A heart disease that is present at birth. "Taken together, these data demonstrate that dysregulation of Kif1A expression may impair normal heart development via disruption of F-actin organization, suggesting a potentially novel mechanism for some of the most common forms of human congenital heart disease." (PMID 32498427, 2020).
cryptorchidism (1 paper, 2022). The failure of one or both testes of a male fetus to descend from the abdomen into the scrotum during the late part of pregnancy. "KIF1A-related disorders are relatively rare in the general population, but males with pathogenic KIF1A variations have been observed to have tiny testes or penises, as well as cryptorchidism." (PMID 35547823, 2022).
head and neck squamous cell carcinoma (1 paper, 2021). A squamous cell carcinoma that arises from any of the following anatomic sites: lip and oral cavity, nasal cavity, paranasal sinuses, pharynx, larynx, and salivary glands. "KIF1A has been associated with head and neck squamous cell carcinoma and has an important role in cell division." (PMID 33889300, 2021).
hematoma (1 paper, 2017). A hematoma is a collection of blood from a vascular structure into an extravascular space. "Western blot assays showed that, compared with the ICH + control siRNA group, levels of cleaved caspase-3 significantly increased in the ICH + KIF1A-siRNA group in the peri-hematoma cortex." (PMID 29375318, 2017). "In contrast, overexpression of KIF1A reduced protein levels of cleaved caspase-3 in the peri-hematoma cortex compared with the rats treated with vector." (PMID 29375318, 2017). "To investigate further the role of KIF1A in ICH-induced SBI, we first performed a time course assay of KIF1A protein levels in the peri-hematoma cortex by western blot and immunofluorescence staining." (PMID 29375318, 2017).
hereditary sensory neuropathy type IIC (1 paper, 2023). "KIF1A mutations may also result in hereditary sensory neuropathy type IIC (HSN2C) (MIM #614213)." (PMID 37239332, 2023).
hypertrophic cardiomyopathy (1 paper, 2024). A condition in which the myocardium is hypertrophied without an obvious cause. "Overexpression of the Drosophila kif1A ortholog results in a hypertrophic cardiomyopathy phenotype with cardiac valve malformations." (PMID 38370698, 2024).
infantile spasms (1 paper, 2020). A rare epilepsy syndrome characterized by onset of epileptic spasms in infants between 2 and 12 months of age, and rarely up to 24 months. "KIF1A mutation was detected in one of 92 patients with infantile spasms of unestablished etiology." (PMID 32746806, 2020).
mast syndrome (1 paper, 2015). "Such conditions include HSP with thin corpus callosum (SPG11/15 mutations), SPG35/FA2H-associated HSP, Troyer syndrome (SPG20) and Mast syndrome (SPG21), SPG26/B4GALNT1, SPG30/KIF1A, SPG39/PNPLA6 and SPG46/GBA2." (PMID 25480570, 2015).
memory impairment (1 paper, 2023). "KIF1A overabundance in the developing brains of CrT KO mice likely leads to synaptic dysfunction, thus contributing to cognitive and memory impairments." (PMID 37063368, 2023).
molybdenum cofactor deficiency (1 paper, 2016). "We also identified a recurrent de novo mutation in the KIF1A gene and a molybdenum cofactor deficiency caused by the loss of the start codon in the MOCS2A open-reading frame in a mildly affected subject." (PMID 27146152, 2016).
nasopharyngeal carcinoma (1 paper, 2013). A carcinoma arising from the nasopharyngeal epithelium. "In contrast, KIF1A was down-regulated in nasopharyngeal carcinoma and reported as a potential tumoral suppressor." (PMID 24386490, 2013).
neuritis (1 paper, 2023). A neuropathy arising from inflammation of one or more nerves. "In TTLL1 mutant mice, the targeting of KIF1A, a subfamily of kinesin-3 in neuritis, was impaired, but the distribution of KIF3A (kinesin-2) and KIF5 (kinesin-1) was not altered." (PMID 37321451, 2023).
osteosarcoma (1 paper, 2009). A usually aggressive malignant bone-forming mesenchymal neoplasm, predominantly affecting adolescents and young adults. "First, we examined the mRNA expression levels of KIF5B in three cancer cell lines(MCF-7, HeLa and U2OS osteosarcoma) and found it to be highly expressed in allthree cell lines when compared to other N-kinesins including KIF5A/KIF5C(Kinesin 1), KIF3A (Kinesin 2) and KIF1A (Kinesin 3)." (PMID 19242560, 2009).
pancreatic disease (1 paper, 2021). "The predominant axonal involvement seen in our patient, which was attributable to KIF1A involvement, distinguishes this syndrome from the infantile-onset multisystem neurologic, endocrine, and pancreatic disease (IMNEPD) caused by PTRH2 involvement alone." (PMID 33717719, 2021).
paraplegia (1 paper, 2017). Complete paralysis of the lower half of the body including both legs, often caused by damage to the spinal cord. "Among several interesting findings, dominantly inherited KIF1A variants, p.(Val8Met) and p.(Ile27Thr) segregated in two independent families, both presenting with a pure spastic paraplegia phenotype." (PMID 28362824, 2017).
prostate carcinoma (1 paper, 2024). A carcinoma that arises from epithelial cells of the prostate gland. "Targeting KIF1A inhibited the growth of NE differentiated prostate cancer (PCa) cells in vitro and in vivo." (PMID 39505875, 2024).
prostatic adenocarcinoma (1 paper, 2024). "Collectively, we proposed that KIF1A facilitated NE transdifferentiation of prostatic adenocarcinoma via modulation of OGT and O-GlcNAcylation of OCT4 and β-catenin." (PMID 39505875, 2024).
schizophrenia (1 paper, 2026). A major psychotic disorder characterized by abnormalities in the perception or expression of reality. "Additionally, abnormalities in molecular motors such as KIF17 and KIF1A have been implicated in schizophrenia pathophysiology." (PMID 41972553, 2026).
situs inversus (1 paper, 2024). A congenital condition in which there is complete right-to-left reversal of the position of the major thoracic and abdominal organs (that is, they are arranged in a mirror image of the normal positioning). "Mutation of a mouse Kif1a paralog causes situs inversus with left-sided cardiac lesions including BAV." (PMID 38370698, 2024).
small cell neuroendocrine carcinoma (1 paper, 2024). "H&E staining showed that the xenograft tumors derived from LNCaP-AI cells displayed morphological features resembling small cell neuroendocrine carcinoma, including hyperchromatic nucleus and decreased cytoplasm of tumor cells and more necrosis than xenograft with KIF1A knockdown." (PMID 39505875, 2024).
spastic ataxia (1 paper, 2022). "In addition, we also identified one de novo variant in KIF1A (c.761G > A, described as pathogenic) in a patient with spastic ataxia, and confirmed the unaffected parents and sibling did not carry it (family AR49)." (PMID 35326432, 2022).
tauopathy (1 paper, 2025). Neurodegenerative disorders involving deposition of abnormal tau protein isoforms (tau proteins) in neurons and glial cells in the brain. "Neuropathologic assessment of the father, who shared the same KIF1A variants, revealed tauopathy and TDP-43 proteinopathy throughout the brainstem." (PMID 40543705, 2025).
thyroid cancer (1 paper, 2014). "Methylation of KIF1A is known to be frequent and show higher levels in thyroid cancer for example, when compared to normal thyroid tissue." (PMID 24927296, 2014).
vitiligo (1 paper, 2024). Generalized well circumscribed patches of leukoderma that are generally distributed over symmetric body locations and is due to autoimmune destruction of melanocytes. "TYR, TYRP1, Dopachrome Tautomerase (DCT), La-ribonucleoprotein-7 (LARP7), and Kinesin Family Member 1A (KIF1A) were identified as candidate biomarkers for vitiligo with associated immune infiltration." (PMID 38666916, 2024).
neurological disorder (28 papers, 2017 to 2026). "Over the past decade, more than 181 pathogenic KIF1A variants have been identified as the cause of KIF1A-associated neurological disorders (KAND)." (PMID 40427549, 2025). "In humans, pathogenic KIF1A variants have been linked to a broad spectrum of neurological disorders, which are summarized under the umbrella term of KIF1A-associated neurological disorders (KANDs)." (PMID 41585230, 2025). "Although KIF1A-associated neurologic disorders can affect the central nervous system in addition to peripheral nerve, reports that include pathologic studies of the brain are exceedingly rare." (PMID 40543705, 2025). "Pathogenic KIF1A mutations cause KIF1A-associated neurological disorders (KAND), a spectrum of severe neurodevelopmental and neurodegenerative conditions." (PMID 40427549, 2025). "Consistent with KIF1A‐associated neurological disorder in children, Kif1a null mouse showed reduced brain size." (PMID 39932116, 2025). "The group of neurological disorders caused by mutations in the KIF1A gene in human are known as KIF1A-associated neurological disorders, with a diverse range of signs, manifesting as mental retardation, spasticity and epileptic seizures." (PMID 39505875, 2024). "Their findings provide insights into KIF1A’s motility mechanism and potential therapies for associated neurological disorders." (PMID 38956021, 2024). "In 2016, Susannah, a girl of 2 years of age, was diagnosed with KIF1A-associated neurological disorder caused by a mutation in the KIF1A gene." (PMID 39062600, 2024). "Further reports have shown that monoallelic variants in KIF1A are associated with a wide range of neurological manifestations, which are collectively referred to as KIF1A-associated neurological diseases (KANDs)." (PMID 39125740, 2024). "In humans mutations in the KIF1A gene lead to a rare inherited condition collectively known as KIF1A-associated neurological diseases (KANDs)." (PMID 38903095, 2024). "KIF1A-associated neurological diseases (KAND) encompass a spectrum of neurological conditions stemming from alterations in the microtubule motor protein KIF1A due to mutations in the KIF1A gene." (PMID 38846036, 2024). "KIF1A-associated neurological diseases (KANDs) are a group of inherited conditions caused by changes in the microtubule (MT) motor protein KIF1A as a result of KIF1A gene mutations." (PMID 37259299, 2023). "Of note, pathogenic variants affecting the homologous kinesin KIF1A have been proposed to act in a similar manner in autosomal dominant KIF1A-associated neurological disorder." (PMID 37934770, 2023). "KIF1A mutations underlie a wide spectrum of neurodegenerative disorders, broadly termed KIF1A-associated neurological diseases." (PMID 36247768, 2022). "Mutations in KIF1A lead to KIF1A Associated Neurological Disorders (KAND), rare and often misdiagnosed afflictions." (PMID 36549649, 2022). "Mutations of KIF1A in humans can cause a range of afflictions known as KIF1A-associated neurological disorders that include sensory and motor disabilities." (PMID 33082143, 2020). "Finally, we show how OptiPrime can be used to achieve highly streamlined and efficient in vivo correction of a pathogenic mutation in the brain of a mouse model of KIF1A-associated neurological disorder." (PMID 41757025, 2026). "KIF1A-associated neurological disorder (KAND, OMIM 601255) is a rare, neurodevelopmental condition." (PMID 40379967, 2026). "KIF1A, a kinesin-like protein, is typically associated with neurological disorder." (PMID 40630957, 2025). "Pathogenic variants in KIF1A have been associated with a wide spectrum of neurological disorders." (PMID 34121983, 2021). "However, KIF1A expression anomaly was linked with neurological disorders in children." (PMID 35215967, 2022). "KIF1A neurological disorder (KAND) patients are identified in early childhood and have a life expectancy of 5–7 years." (PMID 40552310, 2025).
neurological disorder (continued). "Mutations in KIF1A (resulting in KIF1-associated neurological disorder/KAND), KIF1B (resulting in Charcot-Marie-Tooth disease), KIF5A (resulting in ALS), and KIF21B (causing neurodevelopmental disorders) result in various neurological disorders where intracellular transport defects are evident." (PMID 41277110, 2026). "These advancements in understanding the structural and functional aspects of KIF1A are pivotal for developing targeted treatments, especially for KAND and related neurological disorders." (PMID 38956021, 2024).
neurodegenerative disease (10 papers, 2010 to 2026). A disorder of the central nervous system characterized by gradual and progressive loss of neural tissue and neurologic function. "The microtubule motor KIF1A has a highly conserved role in the trafficking of synaptic vesicle precursors, while mutations in KIF1A are causal for the neurodevelopmental and neurodegenerative disease KIF1A-Associated Neurological Disorder (KAND)." (PMID 41648190, 2026). "The dysfunction of KIF1A is linked to a spectrum of severe neurodevelopmental and neurodegenerative diseases known as KIF1A-associated neurological disorders (KAND)." (PMID 38956021, 2024). "KIF1A is a superprocessive cytoskeletal motor that transports intracellular cargo in neurons and is a target of mutations linked to neurodegenerative diseases." (PMID 36598948, 2023). "A number of human mutations in KIF1A have been identified that lead to neurodegenerative diseases, termed KIF1A-associated neurological disorders (KAND)." (PMID 36598948, 2023). "How mutations in KIF1A protein cause disease is still unclear, and both loss-of-function and gain-of-function mutations have been linked to human neurodevelopmental and neurodegenerative diseases." (PMID 33496723, 2021). "Mutations in KIF1A lead to neurodegenerative diseases including hereditary spastic paraplegia." (PMID 36598948, 2023). "KIF1A dysfunction leads to severe neurodevelopmental and neurodegenerative diseases in human, such as optic nerve atrophy." (PMID 39505875, 2024). "Our results suggest that KIF1A can be impacted by oxidative stress and raise the possibility that oxidized KIF1A may be involved in the pathogenesis of neurodegenerative diseases." (PMID 42001941, 2026). "Endogenous expression of these VUSs in KIF1A disrupts TDP-43 cellular interactions in human iPSC motor neuron cultures and elicit neuronal architectural deficits similar to those observed in neurodegenerative diseases." (PMID 40543705, 2025).
tumor (9 papers, 2020 to 2025). "The mean tumor weight in the LNCaP-AI xenografts with KIF1A knockdown was 0.0226 ± 0.0056 g, which was significantly lower than that in the control group with the mean tumor weight of 0.4234 ± 0.03369 g (p <0.0001)." (PMID 39505875, 2024). "More importantly, our data revealed that OGT was critical for KIF1A induced NE differentiation and aggressive tumor growth." (PMID 39505875, 2024). "The mean tumor volume in the LNCaP-AI xenografts with KIF1A knockdown was 79.15 ± 16.83 mm3, while the control group was 383.5 ± 51.69 mm3 (p <0.0001)." (PMID 39505875, 2024). "Only KIF1A has exhibited a statistically significant decrease in tumor tissues compared to normal tissues." (PMID 34557409, 2021).